MECOM (MDS1 and EVI1 complex locus)
Description:
[Isoform 1]: Functions as a transcriptional regulator binding to DNA sequences in the promoter region of target genes and regulating positively or negatively their expression. Oncogene which plays a role in development, cell proliferation and differentiation. May also play a role in apoptosis through regulation of the JNK and TGF-beta signaling. Involved in hematopoiesis. [Isoform 7]: Displays histone methyltransferase activity and monomethylates 'Lys-9' of histone H3 (H3K9me1). Probably catalyzes the monomethylation of free histone H3 in the cytoplasm which is then transported to the nucleus and incorporated into nucleosomes where SUV39H methyltransferases use it as a substrate to catalyze histone H3 'Lys-9' trimethylation. Likely to be one of the primary histone methyltransferases along with PRDM16 that direct cytoplasmic H3K9me1 methylation.
Synonyms: EVI1; MDS1; PRDM3; MDS1-EVI1; KMT8E; AML1-EVI-1; RUSAT2
Tractability: PROTAC: UniProt records ubiquitination sites on it; ubiquitination databases record sites on it.
Target class: Enzyme; Transferase
Gene: Protein-coding gene on chromosome 3 (169,083,499 to 169,663,775, reverse strand). Ensembl gene ENSG00000085276.
Subcellular location: Nucleus; Nucleus speckle; Cytoplasm
Subcellular location (Human Protein Atlas): Nuclear speckles
Pathways (Reactome):
Chromatin organization: PKMTs methylate histone lysines
Developmental Biology: Formation of the nephric duct
Signal Transduction: Regulation of PTEN gene transcription
Gene Ontology:
Molecular function: DNA-binding transcription factor activity; protein binding; DNA binding; DNA-binding transcription activator activity, RNA polymerase II-specific; histone H3 methyltransferase activity; histone H3K9 methyltransferase activity; histone H3K9 monomethyltransferase activity; RNA polymerase II cis-regulatory region sequence-specific DNA binding
Biological process: negative regulation of DNA-templated transcription; negative regulation of JNK cascade; negative regulation of programmed cell death; positive regulation of DNA-templated transcription; regulation of cell cycle; hematopoietic stem cell proliferation; heterochromatin organization; regulation of transcription by RNA polymerase II; chromatin remodeling; positive regulation of transcription by RNA polymerase II
Cellular component: cytoplasm; histone deacetylase complex; nuclear speck; nucleus; cytosol; nucleoplasm
Genetic constraint (gnomAD): Loss-of-function variants: 10 observed, 105.59 expected, observed/expected ratio (o/e) 0.0947, 90% interval 0.057 to 0.16. The upper end of that interval is the gene's LOEUF score, 0.16, which puts it in group 1 of 6, group 1 being the genes least tolerant of losing a copy. Missense variants: 1,248 observed, 1,505 expected, observed/expected ratio (o/e) 0.83, 90% interval 0.79 to 0.87. Synonymous variants: 501 observed, 535.21 expected, observed/expected ratio (o/e) 0.94, 90% interval 0.87 to 1.01.
Gene-disease validity (ClinGen):
ClinGen rates the evidence that MECOM causes each of these diseases.
MECOM-associated syndrome (autosomal dominant): Definitive. Any syndrome in which the cause of the disease is a mutation in the MECOM gene.
Homologues: Orthologues: chimpanzee MECOM (99% identical), dog MECOM (97% identical), pig MECOM (97% identical), rabbit MECOM (96% identical), rat Mecom (93% identical), macaque MECOM (90% identical), guinea pig MECOM (82% identical), mouse Mecom (79% identical), tropical clawed frog mecom (67% identical), zebrafish mecom (37% identical), Drosophila melanogaster ham (25% identical), Caenorhabditis elegans egl-43 (16% identical), and 1 more. Paralogues in human: PRDM16 (53% identical).
Diseases named in the same sentence as MECOM in open-access papers:
MECOM is named in the same sentence as 102 diseases in open-access papers, as found by Europe PMC text mining. Sharing a sentence is not in itself a finding about the gene and the disease. The quoted sentences say what the papers report.
acute myeloid leukemia (34 papers, 2008 to 2026). Acute myeloid leukemia (AML) is a group of neoplasms arising from precursor cells committed to the myeloid cell-line differentiation. "An aggressive subtype of acute myeloid leukemia (AML) is caused by enhancer hijacking resulting in MECOM overexpression." (PMID 39853740, 2026). "MECOM overexpression has been reported in ~10% of adult and pediatric acute myeloid leukemias (AMLs) and is associated with a particularly poor prognosis." (PMID 36522544, 2023). "Notably, the oncogene MECOM, implicated in acute myeloid leukemia and other hematologic malignancies, was among the top 25 genes, with mutations concentrated in SIRs." (PMID 41153425, 2025). "MECOM is a transcriptional regulator of the NF-κβ-mediated inflammatory response and an oncogene whose upregulation has been associated with many types of solid cancers in humans, including colorectal cancer and acute myeloid leukemia." (PMID 37821814, 2023). "The EVI1 protein, encoded by the MECOM gene, is a multifunctional transcription factor critical in various hematological malignancies, particularly acute myeloid leukemia (AML)." (PMID 39468462, 2024). "High-risk acute myeloid leukemia (AML) frequently exhibits increased expression of the transcription factor MDS1 and EVI1 complex locus protein (MECOM), which is essential for hematopoietic stem cells in healthy states." (PMID 40991835, 2025). "For example, in acute myeloid leukemia, MECOM gene fusion and amplification mark aggressive disease and poor survival rate." (PMID 40664642, 2025). "Acute myeloid leukemia (AML) driven by the activation of EVI1 due to chromosome 3q26/MECOM rearrangements is incurable." (PMID 38748792, 2024). "Among 113 CMML patients, 23(20.4%)were re-diagnosed as acute myeloid leukemia(AML), including 18 AML with NPM1 mutation, 3 AML with KMT2A rearrangement, and 2 AML with MECOM rearrangement." (PMID 37550186, 2023). "It is well established that chromosomal rearrangements or proviral insertion at the PRDM3 locus gene, MECOM, are found in up to 10% of acute myeloid leukemia (AML) cases with poor survival outcomes." (PMID 32290321, 2020). "For example, a chromosomal rearrangement in acute myeloid leukemia (AML) was found to bring an enhancer into the proximity of the oncogenic MDS1 and EVI1 complex locus (MECOM), precipitating the malignancy." (PMID 31067678, 2019). "Others loci are associated with hematological disorders such as CEBPA, FOXP1, MECOM and RHOH which promotes Acute myeloid leukemia, diffuse large B-cell lymphoma, myeloproliferative neoplasm and B-cell chronic lymphocytic leukemia respectively." (PMID 31105870, 2019). "In acute myeloid leukemia (AML), the MDS1 and EVI1 complex locus - MECOM, also known as the ecotropic virus integration site 1 - EVI1, located in band 3q26, can be rearranged with a variety of partner chromosomes and partner genes." (PMID 25071866, 2014).
leukemia (30 papers, 2008 to 2026). A malignant (clonal) hematologic disorder, involving hematopoietic stem cells and characterized by the presence of primitive or atypical myeloid or lymphoid cells in the bone marrow and the blood. "Like MYC, MECOM is another transcription factor which can activate proliferation gene programs, and translocations of MECOM have recently been included as adverse risk factors in leukemia classification guidelines." (PMID 41008781, 2025). "Genetic alterations have been described, such as the MECOM gene related to cell development and differentiation, more frequent in leukaemia, which when present in ovarian cancer, is associated with a better prognosis and a longer disease-free interval." (PMID 39272653, 2024). "Positively correlated genes such as MECOM were reported to have pro-leukemia effects and were associated with prognosis in AML." (PMID 35227274, 2022). "Genes controlled by SETBP1 such as MECOM are significantly upregulated in leukemias containing SETBP1 mutations." (PMID 29875417, 2018). "Is AF4 a potential link between MECOM-rearranged leukemia and CTCF pathways, given that both bind to acetylated H3K9/18/27?" (PMID 40255434, 2025). "Functional genomic screens were employed to identify MECOM-controlled cisREs that are essential in facilitating MECOM’s ability to block differentiation in stem cell–like leukemia cells." (PMID 40991835, 2025). "MECOM, first identified as a marker of poor prognosis in leukemia, is a complex locus resulting from the fusion of two genes: MDS1 (myelodysplasia syndrome 1) and EVI1 (ecotropic virus integration site 1), located on chromosome 3 (3q26.2)." (PMID 41340866, 2025). "Intriguingly, a recent study demonstrated that the hypomethylating agent 5-aza-2-deoxycytidine can induce widespread apoptosis in MECOM-high leukemia cells, highlighting its potential as a therapeutic agent for leukemia with MECOM overexpression." (PMID 40255434, 2025). "These analyses in primary leukemia and matched remission samples corroborated MECOM’s role in directly repressing a myeloid differentiation cisRE network." (PMID 40991835, 2025). "Remarkably and unexpectedly, a single node in this network, a MECOM-bound cis-regulatory element located 42 kilobase (kb) downstream of the myeloid differentiation regulator CEBPA is both necessary and sufficient for maintaining MECOM-driven leukemias." (PMID 40991835, 2025). "Most of these genes were associated with cancers of metabolic systems (DUSP6, SGK1, BMP4, RASGRF1, GDF15) followed by breast cancer (CACNA2D3, ITGB7), cancers of the central nervous system (PRKCA), or leukemia (MECOM, JAK3)." (PMID 36624125, 2023). "Aberrant expression of MECOM is one of the characteristic features of many malignancies including leukemia and solid tumors such as breast cancer and hepatocellular carcinoma as well as lung cancer." (PMID 36194576, 2022). "On the other hand, the fusion of H2AFY with MDS1 and EVI1 Complex (MECOM) and the downregulation of H2AFZ have been associated with cancer progression in leukemia." (PMID 31906036, 2019). "Since AF4 is one of the partner genes for KMT2A, could therapeutic approaches currently utilized or studied for leukemia with KMT2 rearrangement be applicable to those with MECOM rearrangement?" (PMID 40255434, 2025). "To investigate whether MECOM expression within a leukemia correlates with the differentiation phenotype, we examined signatures from nonmalignant HSCs and monocytes within each cell as well as our 122 gene signature that we had defined to be directly regulated by MECOM." (PMID 40991835, 2025). "In MDS1 and EVI1 complex locus (EVI1)-overexpressing leukemia, PRMT5 inhibition decreased the levels of the spliced cytoplasmic form of activating transcription factor 4 (ATF4) protein, resulting in increased oxidative stress, growth arrest and senescence." (PMID 40603833, 2025).
leukemia (continued). "This set of target genes was also confirmed in leukemias induced in mice transformed by MLL-AF9 (HoxA9, HoxA10, Evi1 (MECOM), HoxA2, HoxA7 HoxA3, and HoxA13) and also induced iMLL-AF9 in mice HoxA9, HoxA10, Meis1, Eya1, Mef2c, Myb, and Six1." (PMID 34639154, 2021). "HSC signatures were significantly more abundant in AMLs expressing MECOM, whereas monocyte signatures were significantly more abundant in leukemias lacking MECOM." (PMID 40991835, 2025). "Is there any molecular mechanistic overlap between MECOM and KMT2A rearranged leukemia?" (PMID 40255434, 2025). "In an orthogonal interrogation of cisRE function, we next investigated whether the activation of any single MECOM-repressed element, in the absence of MECOM perturbation, is sufficient to induce differentiation of stem cell–like leukemia cells." (PMID 40991835, 2025). "To directly elucidate MECOM-driven transcriptional and epigenetic programs in stem cell–like leukemia cells, we engineered 3 AML cell line models with a 2xHA-FKBP12F36V-P2A-enhanced green fluorescent protein (eGFP) cassette at the C-terminus of the endogenous MECOM locus." (PMID 40991835, 2025).
ovarian carcinoma (19 papers, 2009 to 2025). A malignant neoplasm originating from the surface ovarian epithelium. "The anti-tumorigenic effects due to MECOM loss were phenocopied by the treatment of ovarian cancer cells harboring MECOM amplification with JIB-04 epigenetic inhibitor targeting Jumonji domain histone demethylase enzymes." (PMID 40664642, 2025). "Collectively, our data indicate that PAX8 and MECOM splice variants, including the ovarian cancer-specific PRDM3, reside in the same protein complex." (PMID 33903593, 2021). "Our study in ovarian cancer epithelial cells consistently showed that MECOM loss, as well as JIB-04 treatment, downregulated ZEB1 along with its non-canonical targets, N-cadherin and vimentin, suggesting potential transcriptional regulation of N-cadherin and vimentin." (PMID 40664642, 2025). "In this study, we report that MECOM promotes cellular proliferation and migration in ovarian cancer cells harboring MECOM amplification and pinpoint cisplatin resistance as an intrinsic property of MECOM-amplified ovarian cancer cells." (PMID 40664642, 2025). "Towards this end, we identified JIB-04, a Jumonji-domain histone demethylase inhibitor, as a potential epigenetic targeted therapy for ovarian cancers harboring MECOM amplification." (PMID 40664642, 2025). "In our study, ovarian cancer cells harboring MECOM amplification showed higher cisplatin resistance compared to cells lacking amplification." (PMID 40664642, 2025). "Altogether, these data suggest that epigenetic silencing of MECOM by JIB-04 mediated H3K27me3 modulation is an important mechanism in ovarian cancer and provide a new therapeutic target for the treatment of ovarian cancers harboring MECOM amplification." (PMID 40664642, 2025). "Loss of MECOM experiment was performed to understand its oncogenic function in SKOV3 and OVSAHO ovarian cancer cells that harbor MECOM amplification." (PMID 40664642, 2025). "Our findings reveal that JIB-04 exerts anti-tumorigenic effects in ovarian cancer cell-derived mouse xenografts by inhibiting MECOM/KRAS-mediated proliferation signaling." (PMID 40664642, 2025). "RNAi-mediated attenuation of MECOM in ovarian cancer cells harboring MECOM amplification reduced their proliferation, impaired colony formation, and impeded cellular migration." (PMID 40664642, 2025). "MECOM displayed a cancer-promoting role in ovarian cancer cells with MECOM amplification, which intrigued us to look for MECOM inhibitors in the literature." (PMID 40664642, 2025). "Our study establishes the epidrug JIB-04 as a promising therapeutic agent for targeting the amplified oncogene MECOM in ovarian cancer." (PMID 40664642, 2025). "The selected amplified ovarian cancer cells exhibited MECOM protein overexpression, and abrogating endogenous MECOM expression in these cells disrupted key cancer characteristics, including enhanced proliferation and migration." (PMID 40664642, 2025). "The Cancer Genome Atlas (TCGA) indicates that in addition to ovarian cancer, MECOM is also copy-number amplified in >5% cases in various cancers." (PMID 40664642, 2025). "We reveal that MECOM-mediated transcriptional regulation of KRAS activates KRAS/ERK/EGR1 signaling axis, contributing to MECOM’s oncogenic activity in MECOM-dependent ovarian cancers." (PMID 40664642, 2025). "In this study, we identified the oncogenic function of MECOM gene in ovarian cancer cells harboring MECOM copy number amplification." (PMID 40664642, 2025). "The copy number amplification coincided with higher MECOM expression in patients of ovarian cancer compared to healthy controls as analysed by pan-cancer microarray datasets HG-U133 microarray (GPL570 platform)." (PMID 40664642, 2025). "MDS1 and EVI1 Complex locus (MECOM) gene is copy number amplified and overexpressed in aggressive epithelial ovarian cancers." (PMID 40664642, 2025).
ovarian carcinoma (continued). "Screening for potential epidrugs with MECOM-modulatory function identified E-JIB-04 as a potent inhibitor with growth inhibitory properties and the ability to enhance cisplatin sensitivity of ovarian cancer cells harboring MECOM amplification." (PMID 40664642, 2025). "Further, we evaluated MECOM expression in two independent patient datasets comprising of tumor samples from ovarian cancer patients and ovarian tissues from healthy volunteers." (PMID 40664642, 2025). "A physical crosstalk between PAX8, commonly expressed in tubal epithelium, and the gene locus of EVI1 (MECOM) was investigated, using several ovarian cancer cell lines." (PMID 37525239, 2023). "Intriguingly, we found only 643 genes (365 down and 278 up) regulated in response to MECOM knockdown in ovarian cancer cell SKOV3." (PMID 37185814, 2023). "Combined, this study lays the foundation for studying PAX8 and MECOM as therapeutic targets for epithelial ovarian cancer." (PMID 33903593, 2021). "These different responses to PAX8 or MECOM knockdown is suggestive of a weaker contribution of MECOM to ovarian cancer growth, possibly due to its cofactor activity." (PMID 33903593, 2021). "Collectively, our data suggest that PAX8 is a major TF in ovarian cancer cells by engaging a large number of genomic sites, while PRDM3 (MECOM) is specifically recruited by PAX8 at specific genomic loci to modulate a defined common gene module." (PMID 33903593, 2021). "In concordance with earlier studies we observed MECOM copy number gains in more than two thirds of the primary tumors of ovarian cancer patients." (PMID 29290959, 2017). "Our data suggest that CTCs detected by the multi-marker protein panel and/or MECOM/HHLA1 FISH represent minimal residual disease in optimally debulked ovarian cancer patients." (PMID 29290959, 2017). "This region contains the MECOM, SnoN/SKiL, and ECT2 genes all of which have been implicated in ovarian cancer pathogenesis." (PMID 23289505, 2013). "The biological function and precise molecular mechanism of MECOM in the progression and drug resistance of ovarian cancer remain unclear." (PMID 40664642, 2025). "Thus, unraveling contribution of MECOM and its epigenetic modulation in mediating tumor progression and cisplatin resistance in ovarian cancer needed further investigation." (PMID 40664642, 2025). "Similarly, JQ-1, a bromodomain and extraterminal (BET) inhibitor has been shown to inhibit the expression of MECOM and ovarian cancer tumorigenesis." (PMID 41340866, 2025). "This prompted us to investigate whether MECOM transcription could be regulated by epigenetic mechanisms, specifically histone methylation in ovarian cancer." (PMID 40664642, 2025). "Notably, expression analysis of MECOM in GSE14407 dataset showed significantly higher MECOM expression in ovarian cancer patient samples (n = 12) in comparison to normal ovarian surface epithelium samples (n = 12)." (PMID 40664642, 2025). "Having established oncogenic function of MECOM in ovarian cancer, we asked if MECOM copy number amplification and its high expression might correlate with drug resistance in tumor cells." (PMID 40664642, 2025). "Hence, characterizing the biological function of MECOM in ovarian cancer is critical to develop strategies for therapeutically targeting this amplified oncogene." (PMID 40664642, 2025). "Importantly, available ChIP-Seq data of MECOM in human ovarian carcinoma cells also showed direct binding to the promotor regions of Col4a2 and Itga2." (PMID 33762742, 2021). "PRDM3 is amplified in ovarian cancers and we show that the MECOM locus and PAX8 sustain in vivo tumor growth, further supporting that the identified function of the MECOM locus underlies PAX8-driven oncogenic functions in ovarian cancer." (PMID 33903593, 2021). "The impact of epigenetic modulation on MECOM-driven oncogenesis in ovarian cancer remains unknown." (PMID 40664642, 2025).